CTSK (cathepsin K)
Diseases named in the same sentence as CTSK in open-access papers (continued):
Sharing a sentence is not in itself a finding about the gene and the disease.
cancer (continued). "However, the relationship between CTSK expression and the recurrence of other cancers has been studied." (PMID 36052250, 2022). "This suggests that there is some connection between the role of exosomes in CTSK and cancer." (PMID 36005209, 2022). "Cathepsin K may degrade extracellular membrane proteins and destroy the elastic lamina of blood vessels, supporting its role in cancer invasion and progression." (PMID 34069976, 2021). "Based on previous studies, we hypothesize that the highly active TRAP 5b isoform is correlated to aggressiveness in cancers, and that CtsK is involved in activation of TRAP by cleaving TRAP 5a to TRAP 5b." (PMID 32188406, 2020). "Furthermore, CtsK expression and activity have been reported in a variety of cancers and cancer cell lines leading to similar phenotype than high TRAP expression." (PMID 32188406, 2020). "However, CtsK-inhibiting treatment was able to reduce secretion TRAP 5a from TRAP-overexpressing cancer cells." (PMID 32188406, 2020). "Cathepsin K is isolated into lysosomes through the endosome, and it can also be secreted into the other compartments of the cell and extracellular environment, which is essential for its role in promoting the development of cancer cells in tumors." (PMID 32927648, 2020). "IL-20 induces the expression of MMP9, MMP-12, RANKL, cathepsin K and cathepsin G in cancer cells." (PMID 29690863, 2018). "Cathepsin K has been shown to have a significant role in many diseases, such as osteoarthritis and rheumatoid arthritis, atherosclerosis, the progression of cerebral aneurysms, and cancer progression." (PMID 23951042, 2013). "In cutaneous squamous cell carcinoma, cathepsin K in stromal tissue facilitates cancer invasion." (PMID 23951042, 2013). "In carcinomas, cathepsin K was present in both carcinoma and stromal cells." (PMID 23951042, 2013). "Cathepsin K is expressed in OTSCC tissue in both carcinoma and TME cells." (PMID 23951042, 2013). "Strong CTSK expression was related to poor clinicopathological parameters such as (high-grade carcinomas, large infiltrating carcinomas, presence of nodal involvement, presence of distant metastasis, carcinomas of advanced TNM clinical stage, presence of recurrence, and reduced DFS)." (PMID 37198626, 2023). "Based on the role of CTSK in a variety of cancers, it may serve as a potential biomarker." (PMID 36005209, 2022). "Therefore, the combination of cathepsin K inhibition and anticancer drugs may provide a novel and effective strategy for cancer therapy." (PMID 34785775, 2022). "However, in this manuscript, we focus on the role of CTSK in cancer." (PMID 36005209, 2022). "Consequently, CTSK may serve as a versatile therapeutic target for various human cancers, and the inhibition of CTSK is of great significance for the treatment of cancers." (PMID 36005209, 2022). "Importantly, CTSK has some advantages and specificity in cancer diagnosis, owing to the physiological functions of CTSK, including mediating bone resorption, degrading the extracellular matrix, participating in bone remodeling and other physiological activities." (PMID 36005209, 2022). "We further tested whether FOXF2-regulated CTSK secretion by cancer cells induce osteoclastogenesis." (PMID 31222004, 2019). "CTSK facilitates the degradation of the ECM, enabling the migration and proliferation of cancer cells that explains the strong expression which was observed in carcinomas of aggressive behavior." (PMID 37198626, 2023). "Therefore, cathepsin K inhibitor may be an effective candidate for anti-cancer adjuvants." (PMID 37330581, 2023). "In vivo studies demonstrated that CTSK plays an key role in the gene induction program regulated by TLR9 signaling, and CTSK-dependent TLR9 signaling in DCs contributes to cancer metastasis and autoimmune inflammation." (PMID 37935734, 2023). "In this study, we demonstrated that a cathepsin K inhibitor (ODN) induces Raptor destabilization and enhances mitochondrial dysfunction in cancer cells." (PMID 37330581, 2023).
cancer (continued). "CTSK was often found to be strongly related to M2 in carcinoma of both localized PC and CRPC when the correlation curves were used to further verify the relationship between CTSK and CD206 by immunofluorescence experiment and ELISA." (PMID 36138018, 2022). "Cathepsin K is able to cleave and activate pro-MMP-9 and is involved in inflammation and in some types of cancer." (PMID 35723387, 2021). "WB and IF assays showed that the expression level of Cathepsin K in A549 was higher than that in MRC-5, which is consistent with the conclusion that Cathepsin K is highly expressed in cancer tissues and cells in the literature." (PMID 32927648, 2020). "Here, we investigated CtsK as a potential activator of TRAP processing, localization and trafficking, as well as functional activity in a TRAP-overexpressing cancer cell line that has been previously characterized." (PMID 32188406, 2020). "We present the effects of CtsK-activity on TRAP expression and function in a TRAP-overexpressing MDA-MB-231 cancer cell line." (PMID 32188406, 2020). "CTSK protein expression was also increased in bone metastatic tissues formed by MDA-MB-231 cells, especially in cancer cells adjacent to osteolytic bone lesions." (PMID 31222004, 2019). "Conversely, CTSK knockdown attenuated the number and size of TRAP+ osteoclasts induced by the CM from FOXF2-overexpressing cancer cells." (PMID 31222004, 2019). "Previous studies reported that MMP-12, MMP-9, and cathepsin K accelerate extracellular matrix (ECM) degradation leading the invasion and metastasis of cancer cells." (PMID 29690863, 2018). "The expression of cathepsin B and X was detected in stromal cells and cancer cells throughout the GBM sections, whereas cathepsin K expression was more restricted to arteriole-rich regions in the GBM sections." (PMID 30046941, 2018). "Our aim was to describe the expression of cathepsin K in invasive OTSCC in vitro and in a series of clinical cancer specimens." (PMID 23951042, 2013). "Some cancer-related genes are located in these highly common, early appearing RARs: MCL1, CTSK, ARNT, S100A10, PTK2, PTP4A3, and PSCA in the RAR-Gs; and DLC1, PINX1, and GATA4 in the RAR-Ls." (PMID 22938721, 2012). "Our findings demonstrate that cathepsin K inhibition induces OTUB1 dephosphorylation-mediated Raptor destabilization through Syk-SHP2 activation leading to an increase in mitochondrial dysfunction and anti-cancer sensitivity." (PMID 37330581, 2023). "Cathepsin K, OPG, and NF-kB play a crucial role in osteolysis and cancer cell migration." (PMID 36674719, 2023). "CTSK significantly revealed strong expression in large-sized carcinomas (19 cases, 73.1%), while small-sized carcinomas showed negative (7 cases, 36.8%) and weak (6 cases, 31.6%) expression." (PMID 37198626, 2023). "This led to the hypothesis that CtsK also mediates TRAP processing, i.e. generation of high TRAP 5b levels in the MDA-MB-231 TRAP-overexpressing cancer cells." (PMID 32188406, 2020). "To determine whether the microenvironment of cancer cells in BICA and IVBL are similar, we performed immunofluorescent staining of alkaline phosphatase (ALP), collagen I (Col-I) and cathepsin K (CTSK)." (PMID 28429794, 2017). "In the ten primary cancer cases with corresponding lymph node metastases analyzed, we observed that metastatic OTSCC cells in lymph nodes were also positive for cathepsin K." (PMID 23951042, 2013). "In our 121 OTSCC patient samples, cathepsin K was detected in the great majority of cancers (only 4 cases were negative), including a few dysplastic areas surrounding the carcinoma tissue, as well." (PMID 23951042, 2013).
cancer (continued). "Some carcinomas contained multinucleated giant cells, which always stained intensively for cathepsin K, similar to osteoclasts of the bone (not shown)." (PMID 23951042, 2013). "Cathepsin K was expressed in a majority of carcinoma and metastatic cells, but the expression pattern in carcinoma cells did not correlate with clinical parameters." (PMID 23951042, 2013). "Phenotypic resemblance of OGCs to the osteoclasts in the bone was confirmed with expression of MMP9, TRAP, and cathepsin K. The OGCs were negative for HLA-DR, and lacked antigen presentation abilities as anti-cancer defence." (PMID 20731838, 2010). "large sized carcinomas (T3 and T4) showed mainly strong (19 cases, 73.1%) and moderate (4 cases, 15.4%) expression, while small-sized carcinomas (T1 and T2) showed negative (7 cases, 36.8%) and weak (6 cases, 31.6%) CTSK expression." (PMID 37198626, 2023). "However, increasing current studies have also suggested that some non-osteoclast cell types also express CTSK, which would be upregulated when the cancers occurred." (PMID 36005209, 2022). "Therefore, CtsK-inhibiting treatments of cancer progression are not likely to be mediated through TRAP-processing within cancer cells, but through decrease in secretion of growth factor–like TRAP 5a." (PMID 32188406, 2020). "Instead, the weak expression of cathepsin K in the invasive TME front correlated with increased overall recurrence (p<0.05), and in early-stage tumors this pattern predicted both cancer recurrence and cancer-specific mortality (p<0.05 and p<0.005, respectively)." (PMID 23951042, 2013). "However, the myoma tissue, in the absence of invading carcinoma cells, also had detectable levels of cathepsin K immunoreactivity, as did the fibroblasts embedded in the collagen gel." (PMID 23951042, 2013). "However, the effect of cathepsin K inhibition in cancer cells is not well characterized." (PMID 34785775, 2022).
infection (13 papers, 2009 to 2025). The state of being infected such as from the introduction of a foreign agent such as serum, vaccine, antigenic substance or organism. "Five days after infection, we collected femur samples to perform immunofluorescence staining and found abundant signals in osteoclasts (cathepsin K, CTSK+), osteoblastic cells (osterix, Osx+), and leukocytes (cluster of differentiation 45, CD45+) in the bone." (PMID 38097598, 2023). "When using pseudotyped HIV, a high efficiency of infection at 12 dpi was observed irrespectively of the HIV-VSV inoculum accompanied in both for a high level of CTSK expression." (PMID 37404829, 2023). "All three collagenases (MMP1, MMP13 and CTSK) tested demonstrated increased expression in response to infection." (PMID 34805001, 2021). "Cathepsin K protein levels were assessed 6 hours after feeding on Day 3 and increase protein expression was also observed following AdTIEG1 infection." (PMID 21423731, 2011). "Besides that, the Cathepsin K knockout shed new light on the role of dendritic cells and subsequent immune cell influx, thereby modulation severity of the infection." (PMID 29163477, 2017). "Moreover, the black rockfish that were treated with CTSS knockdown showed clearly higher bacteria amounts versus the control after the infection, while the fish that underwent the CTSK knockdown exhibited significantly lower bacterial amounts than the control group." (PMID 40422803, 2025). "Additionally, the osteoclast marker protein CTSK was upregulated following infection but returned to baseline levels after DUSP4 overexpression, indicating a protective effect against infection-induced bone resorption." (PMID 40177487, 2025).
cardiovascular disease (8 papers, 2015 to 2026). "Cathepsin K, S, and V have been shown to play a role in cardiovascular diseases by causing excessive elastin degradation." (PMID 35501334, 2022). "Increased levels of certain enzymes, such as hyaluronidase, matrix metalloproteinases (MMPs), and cathepsin K (CTSK), have been linked to AS and cardiovascular diseases." (PMID 37698552, 2023). "Our current study adds cathepsin K to the repertoire of proteases that play a critical role in regulating cardiac function, thus broadening the potential target for treating cardiovascular disease." (PMID 28821796, 2017). "Recent evidence suggests cathepsin K plays a significant role in the progression of cardiovascular diseases, as well as in the modulation of adiposity and glucose intolerance." (PMID 28821796, 2017).
bone disorder (6 papers, 2011 to 2025). "Notably, genes such as CSRP2, DDX1, RHBDL1, SEZ6L, and CTSK are involved in growth, development, locomotion, and bone disorders." (PMID 38788487, 2024). "It is known that GAGs, including DS and HS, inhibit the collagenolytic activity of cathepsin K,53,54 and that impaired osteoclast function is very important in the pathogenesis of the MPS-IH skeletal disease." (PMID 40821853, 2025).
cardiac disease (5 papers, 2015 to 2022). "Researchers have conveyed that CTSK may become an alternative therapeutic target for cardiac disease." (PMID 32620106, 2020). "Cathepsin K may represent a viable drug target to treat cardiac disease." (PMID 29880809, 2018).
genetic disorder (2 papers, 2013 to 2017). "The function of cathepsin K in osteoclasts was first revealed by the finding of a loss of function mutation in the human cathepsin K gene in patients with pycnodysostosic, a rare genetic disorder characterized by impaired osteoclastic bone resorption." (PMID 26237142, 2013).
inflammation (2 papers, 2024). Aberrant reaction of the microcirculation characterized by movement of fluid and leukocytes from the blood into extravascular tissues. "Our previous work also indicated that disturbed flow increased the expression of cathepsin K, which contributed to endothelial inflammation and vascular remodeling, leading to atherogenesis." (PMID 38414635, 2024). "TRAP+ and CTSK+ macrophage and MNGC accumulations were prominent within alveolar spaces surrounding small conducting airways and in focal areas of chronic interstitial inflammation adjacent to fibrotic regions." (PMID 38985878, 2024).
lung (1 paper, 2011). "In Apoe-/- mice, 41% of the animals displayed lung granulomas, whereas in their cathepsin K-deficient littermates this number reached 88%." (PMID 21251246, 2011). "When compared to wild-type litters, more cathepsin K-deficient mice had lung granulomas, but individually affected mice developed smaller granulomas that were present in lower numbers." (PMID 21251246, 2011). "Apoe-/- mice lacking cathepsin K have shown a higher incidence of lung granulomas compared to Apoe-/- mice, but the size of granulomas was significantly smaller." (PMID 21251246, 2011).
CTSK also shares sentences with these, for which no sentence is quoted: aortic aneurysm (3 papers); breast tumors (3); chronic kidney disease (3); myeloma (3); Paget disease (3); skeletal dysplasia (3); adenocarcinoma (2); basal cell carcinoma (2); chromophobe carcinomas (2); Chronic Heart Failure (2); cystic renal cell carcinoma (2); granular cell tumor (2); hypophosphatasia (2); kidney damage (2); osteonecrosis (2); papillary renal cell carcinoma (2); sclerosteosis (2); tuberculosis (2); acute coronary syndrome (1); adenosquamous carcinoma (1); anemia (1); ankylosing spondylitis (1); autosomal recessive osteopetrosis (1); basaloid squamous cell carcinoma (1); Blindness (1); bone fracture (1); cartilage disease (1); central nervous system disease (1); central nervous system tuberculosis (1); cervical cancer (1).
A further 73 diseases each share a sentence with CTSK in 1 paper.